SNHG17 (small nucleolar RNA host gene 17)
Diseases named in the same sentence as SNHG17 in open-access papers (continued):
Sharing a sentence is not in itself a finding about the gene and the disease.
tumor (32 papers, 2019 to 2025). "SNHG17 has been demonstrated to exhibit a high capacity to modulate the expression of specific targets closely associated with tumor cell proliferation, apoptosis, invasion, migration, amongst others." (PMID 35248073, 2022). "Although SNHG17 has been implicated in tumor development, its role in regulating G1/S transition via c-Myc has not been reported yet." (PMID 34671012, 2021). "Specifically, high SNHG17 expression levels were closely associated with advanced pathological features (tumor size, lymph node invasion, and distant organ metastasis) and the dismal survival of RCC patients." (PMID 34497156, 2021). "Several studies have demonstrated that SNHG17 is closely related to the proliferation, migration, invasion, apoptosis, and chemical drug resistance of tumor cells, and clinical studies have found an association between high SNHG17 expression and poor prognosis." (PMID 35248073, 2022). "Nevertheless, results may be different between experiments in vivo and in vitro, due to some causes such as the tumor microenvironment, and animal study is needed to further explore the role of SNHG17 in vivo." (PMID 34557456, 2021). "SNHG17 has been reported to act as an oncogene that promotes tumor cell proliferation and migration while inhibiting apoptosis." (PMID 38300330, 2024). "Chr 2: Small nucleolar RNA host gene 17 is expressed in nervous system, acts as a sponge for multiple miRNAs, such as miR-23a-3p, miR-485-5p, and miR-361-3p, promoting tumor progression in various malignancies." (PMID 37987368, 2023). "While information regarding the role of SNHG17 in the tumor immune microenvironment remains limited, our study aims to delve into its involvement specifically in tumor-associated macrophages from PDAC." (PMID 38098044, 2023). "Intriguingly, SNHG17 has been shown to reduce Parkin-dependent mitochondrial autophagy by regulating Parkin proteins in non-tumor diseases." (PMID 36185210, 2022). "For example, SNHG17 exerts a pro-tumor effect in CRC by sponging miR-23a-3p and upregulating CXCL12." (PMID 35248073, 2022). "For reference, STC2, a downstream target of miR-361-3p, was shown to promote tumor invasion and migration via the Wnt/β-catenin signaling pathway in vivo experiments, while SNHG17 acts as a ceRNA for miR-361-3p." (PMID 36185210, 2022). "A recent study demonstrated a positive feedback loop between SNHG17 and its homolog snoRA71B, promoting tumor progression." (PMID 36185210, 2022). "SNHG17 expression is also positively correlated with tumor size and TNM stages, while it is negatively correlated with CRC prognosis." (PMID 35248073, 2022). "Growing evidence has proved that SNHG17 plays a tumor-promoting role in tumorigenesis and development." (PMID 36185210, 2022). "SNHG17 has several transcripts and has been shown to be expressed both in the nucleus and cytoplasm of different tumor cells via fluorescence in situ hybridization (FISH) or nucleo-cytoplasmic separation experiment." (PMID 35248073, 2022). "The mouse xenograft model in vivo suggested that the depletion of SNHG17 prohibited tumorigenesis, whereas overexpression of SNHG17 promoted tumor growth." (PMID 34497156, 2021). "For instance, the lncRNA genes (LINC00324, PTPRGAS1 and SNHG17) have been related to ER+ and ER− subtypes, tumor histologic grade and clinic outcomes." (PMID 33902604, 2021). "Recent reports have confirmed that SNHG17 is abnormally expressed in tumors and acts as a potential regulator of tumor progression." (PMID 34429400, 2021). "Long noncoding RNA small nucleolar RNA host gene 17 (SNHG17) was reported to be a critical regulator of tumorigenesis, and studies have reported its role in promoting tumor invasion and proliferation by activating the PI3K/AKT pathway." (PMID 34040677, 2021).
tumor (continued). "Furthermore, elevated SNHG17 expression was noticeably associated with larger tumor size, poor differentiation, the presence of vascular invasion, advanced TNM stage, and poor prognosis, indicating SNHG17 may be an oncogene which predicts a poor prognosis of HCC patients." (PMID 34557456, 2021). "Immunohistochemistry revealed increased staining for E-cadherin and vimentin in rat tumor tissues as compared to that in the matched normal tissues, suggesting that upregulation of SNHG17 stimulated EMT in HCC." (PMID 33519911, 2020). "Functional assay showed that downregulation of SNHG17 significantly inhibited cell proliferation and migration in vitro, and suppressed tumor growth in vivo." (PMID 32042267, 2020). "Hematoxylin and eosin staining of lung tissues from mice with HCC revealed overexpression of SNHG17 promoted tumor metastasis." (PMID 33519911, 2020). "Our observation of strong tumor-specific co-expression among SNHG17, SNHG1 and PABPC1L; together with the reciprocal association between SNHG17 and RUSC1-AS1 in multivariable models suggest a model in which lncRNA networks and translation regulators act in concert to drive tumor cell phenotypes." (PMID 41357316, 2025). "In short, SNHG17 could induce the polarization of pro-tumor macrophages, facilitating the growth and metastasis of PCs." (PMID 38098044, 2023). "H2AX, which can be regulated by SNHG17, also plays an essential role in tumor angiogenesis." (PMID 36185210, 2022). "We found that downregulation of SNHG17 inhibited tumor cell migration, and cell invasion." (PMID 35719962, 2022). "Studies on whether SNHG17 can regulate Parkin-dependent mitochondrial autophagy and affect tumor progression, which requires further experimental verification in the future, are still unavailable." (PMID 36185210, 2022). "Collectively, we found that SNHG17 exerts tumor-promoting functions through PES1 and FOSL2." (PMID 34782005, 2021). "SNHG17 exerts tumor-promoting functions by two different mechanisms." (PMID 34782005, 2021). "Our findings suggest that lncRNAs represent a new class of c-Myc regulators, and upregulation of SNHG17 in tumors may facilitate tumor growth via c-Myc." (PMID 34671012, 2021). "To summarize, these results indicate that SNHG17 promotes OC tumor growth both in vitro and in vivo and that SNHG17 may play a vital role in cell-cycle regulation in OC." (PMID 32911343, 2020). "Moreover, high expression of SNHG17 correlated with larger tumor size and higher Edmonson-Steiner grades, suggesting that SNHG17 participates in the progression of HCC." (PMID 33519911, 2020). "The expression of SNHG17 was upregulated in BC tissues compared with non-tumor breast tissues." (PMID 32042267, 2020). "However, additional research needs to verify whether SNHG17 can activate the Wnt/β-catenin pathway and thus promote tumor progression through WLS and STC2." (PMID 36185210, 2022). "Notably, Parkin protein was recently found to be regulated by SNHG17 in non-tumor diseases." (PMID 36185210, 2022). "We also uncovered, for the first time, that SNHG17 promotes tumor growth and metastasis via two different regulatory mechanisms, SNHG17-Trim23-PES1 axis and SNHG17-miR-339-5p-FOSL2-SNHG17 positive feedback loop, suggesting that SNHG17 could be a potential therapeutic target for CRC." (PMID 34782005, 2021). "Taken together, SNHG17 may inhibit c-Myc ubiquitination and thus stabilize c-Myc protein by associating with LRPPRC, which leads to upregulation of c-Myc, acceleration of G1/S transition and cell proliferation, and consequent tumor growth." (PMID 34671012, 2021). "Collectively, these results indicate that SNHG17, PABPC1L and SNHG1 form a coordinated expression module in CRC samples and that RUSC1-AS1 is incorporated into this tumor-specific network." (PMID 41357316, 2025). "Our study identified a tumor-specific expression module comprising PABPC1L, SNHG17 and SNHG1, with RUSC1-AS1 incorporated into the tumor co-expression network." (PMID 41357316, 2025).
tumor (continued). "A number of lncRNAs discussed in previous sections, such as SNHG17, MALAT1, XIST, SBF2-AS1, NKILA, and Linc-pint, have been shown to regulate tumor behavior in preclinical studies through their interaction with the TGFβ pathway." (PMID 41437175, 2025). "For instance, SNHG17 and LINC00239 are upregulated and positively correlate with tumor TNM stage, invasion depth, and lymph node metastasis in ESCC." (PMID 41437175, 2025). "In this paired analysis of 43 CRC patients, we found consistent upregulation of PABPC1L, SNHG17 and SNHG1 in tumor tissues relative to ANT samples, while RUSC1-AS1 showed a non-significant trend toward increased expression." (PMID 41357316, 2025). "The study also showed that SNHG17 can act as an endogenous “sponge” by competing with miR-338-3p to regulate SOX4, consequently promoting tumor progression." (PMID 38090151, 2023). "In summary, SNHG17 acted as a ceRNA and modulated PGK1 expression by sponging miR-628-5p, enhancing the polarization and pro-tumor activities of M2-like macrophages." (PMID 38098044, 2023). "This study demonstrates a regulatory relationship between SNHG17 and HDL-C and the possible involvement of SNHG17 in tumor progression through lipid metabolism." (PMID 36185210, 2022). "Thus, targeting SNHG17 may become a promising strategy for tumor therapy." (PMID 36185210, 2022). "Knockdown of SNHG17 significantly suppressed ESCC cell proliferation, invasion, and epithelial–mesenchymal transition in vitro and tumor growth in vivo." (PMID 34429400, 2021). "Mechanistic analysis suggested that SNHG17 acts as an endogenous “sponge” competing with miR-338-3p to regulate SOX4, thereby promoting tumor progression." (PMID 34429400, 2021). "Mechanistically, SNHG17 interacts with PES1 to inhibit the Trim23-mediated ubiquitination of PES1, resulting in increased PES1 stability and enhanced tumor growth and metastasis." (PMID 34782005, 2021). "For instance, SNHG5 is a tumor suppressor in GC, SNHG8 predicts a poor prognosis in GC patients and SNHG17 induces the development of GC." (PMID 31808752, 2019). "Similarly, SNHG17 has been identified as a sponge for miR-375, indirectly promoting PAX6 expression and contributing to tumor proliferation and metastasis." (PMID 40076805, 2025). "Regarding SNHGs, SNHG17 upregulates CXCL12-mediated angiogenesis by sponging miR-23a-3p and forms a positive feedback loop with the Trim23-PES1 axis and miR-339-5p-FOSL2, thereby synergistically promoting tumor proliferation and metastasis." (PMID 41301542, 2025). "These experiments revealed that SNHG17 acted as an oncogene in RCC and promoted tumor progression." (PMID 34497156, 2021). "Moreover, SNHG17 enhances the stability of c-Myc protein by directly binding to LRPPRC and, in turn, promotes G1/S transition and tumor growth." (PMID 34671012, 2021). "Our mechanistic investigations demonstrated, for the first time, that SNHG17 promotes tumor growth and metastasis through two different regulatory mechanisms, SNHG17-Trim23-PES1 axis and SNHG17-miR-339-5p-FOSL2-SNHG17 positive feedback loop, which may be exploited for CRC therapy." (PMID 34782005, 2021). "In addition, these findings were further validated in an independent CRC cohort (NCTs = 107, CRC tissues = 107) and showed that SNHG17 was upregulated in 67.3% (72/107) of CRC tissues compared with their paired NCTs and was positively correlated with tumor stage." (PMID 34782005, 2021).
SNHG17 also shares sentences with these, for which no sentence is quoted: lymph node metastasis (2 papers); type 2 diabetes (2); colon cancer (1); colorectal (1); depression (1); lung squamous cell carcinoma (1); oral squamous cell carcinoma (1).